CCL7 (C-C motif chemokine ligand 7)
Diseases named in the same sentence as CCL7 in open-access papers (continued):
Sharing a sentence is not in itself a finding about the gene and the disease.
infection (157 papers, 2006 to 2026). The state of being infected such as from the introduction of a foreign agent such as serum, vaccine, antigenic substance or organism. "CpG sites linked to Ccl7, Ccl9, Cd74, and Casp8 exhibited the lowest methylation in uninfected samples but increased on Day 1 of infection and then decreased gradually." (PMID 40170749, 2025). "Additional cytokine/chemokine transcripts induced by invasive infection were e.g., Ccl3, Ccl4, Ccl7, Cxcl10, and Csf2 (encoding GM-CSF)." (PMID 38291037, 2024). "When comparing the samples from the patients with different infection severities of the same genetic variant, we noted differences in the CCL7/MCP-3, CXCL9/MIG, and CXCL10/IP-10 concentrations." (PMID 36012323, 2022). "Peptides TAT-I24 and TAT-M26, which were able to cause significant inhibition of ie1 gene expression, also caused a significant reduction of Ifit1, Ccl7 and Ccl5 expression 2 h post-infection." (PMID 35806257, 2022). "Genes encoding interferons (Ifnb, Ifnl2 and Ifnl3), chemokines (Ccl7, Ccl5, and Cxcl10), and ISGs (Ifit1, Ifit2, Ifit3b, Oas3, Ifi44, Rsad2, and Isg15, among others) were prominently represented among those induced by infection in Ifnar1-/- mice." (PMID 34591933, 2021). "Following infection with the 2×scr virus, we observed the most striking differences for Ccl2 and Ccl7, two macrophage-associated chemokines, with ~10-100-fold increase in the testes on day 3 post infection over testes obtained from mock-inoculated mice." (PMID 32614902, 2020). "Given the robust infiltration of immune cells into the cutaneous site of infection, the appearance of parasites in the spleens of CCL7 deficient mice on the C57BL/6 background was unexpected." (PMID 30671055, 2018). "CCL7 is often associated with the positive regulation of myeloid cell recruitment to sites of inflammation and infection." (PMID 30671055, 2018). "L. major infection of CCL7-deficient mice led to an unexpected increase in inflammation in the infected skin 2 weeks post-infection." (PMID 30671055, 2018). "To determine the consequence of CCL7 deficiency on L. major control we analyzed parasite load cutaneously at the site of infection and viscerally in the draining LN and spleen." (PMID 30671055, 2018). "The TLR9 deficient mouse showed reduced CCL7 production, and restoration of CCL7 over the first week of infection relieved the associated suppression of interferon gamma and recruited DC numbers." (PMID 25498576, 2015). "We also established that in CCR2 deficient mice IFN-γ and CCL2 induction by infection with P. chabaudi was similar to infected wild type mice whereas CCL7 was constitutively deregulated." (PMID 23762028, 2013). "Moreover, despite local control of L. major in the dermis, CCL7 deficient mice had slightly elevated parasite burdens in the dLN early in the infection and a striking increase in parasite load in the spleen late in infection." (PMID 30671055, 2018). "Thus, CCL7 deficiency appears to enhance the efficiency of early IL-4-producing effector T cell recruitment and/or retention at the infection site." (PMID 30671055, 2018). "Indeed, genes within the IL-17 pathway including Cebpb, Tnf, IL-6, Cxcl1, Cxcl2, Cxcl3, Cxcl5, Cxcl10, and Ccl7 were shown to be up-regulated in both susceptible and resistant mice during infection." (PMID 29339782, 2018). "The expressions of Ccl7, Ccl9, Cd74, and Casp8 were highest in uninfected samples but decreased on the first day of infection and then gradually increased." (PMID 40170749, 2025). "The monocyte chemoattractants CCL2 and CCL4 were significantly increased in mice infected with both Em and Bb, relative to vehicle or single Bb infection, and CCL7 was significantly increased in co-infected mice relative to Em alone." (PMID 39229265, 2024). "We observed that concentrations of the monocyte chemoattractants CCL2, CCL3, CCL4, CCL5, and CCL7 were significantly increased in mice inoculated with both pathogens, relative to vehicle and single Bb infection." (PMID 39229265, 2024).
infection (continued). "By 24 hours after infection, we also detected increased expression of genes involved in a broader inflammatory response, including Ccl2, Cxcl9, Cxcl10, and Ccl7, which were upregulated across the major LNSC subsets." (PMID 38194268, 2024). "For a subset of patients, we assessed chemokines (CCL2, CCL3, and CCL7) in circulation and at the site of infection." (PMID 36752598, 2023). "In AGM, the expression of Ccl2, Ccl3, Ccl4, Ccl7, and Ccl8 together with Cxcl10 and Cxcl11 also increases during infection, although more rapidly and with a more marked expression in nonpolarized rAM than in hamsters." (PMID 37350967, 2023). "In vivo infection studies were performed by injecting mice with anti-CCL7 antibody/isotype control, IRF7-siRNA/control siRNA." (PMID 37251373, 2023). "Infection led to robust induction of chemokine and interleukin genes, including Il1b, Il6, Ccl2, Ccl3, Ccl4, Ccl7, Cxcl1, Cxcl2, Cxcl5, Cxcl9, and Cxcl10, and related receptor genes, including Ccr1, Ccr4, Ccr5, Ccr5, Ccr7, Cxcr2, Cxcr5, Il1r2, and Il1rn." (PMID 35487885, 2022). "Transcripts encoding cytokines and chemokines such as IL-1β (interleukin-1β), IL-18, IL-6, IFN-γ, IL-10, CCL2 (C-C motif chemokine ligand 2), CCL4 and CCL7 were also up-regulated in the lungs during infection." (PMID 34965194, 2022). "Ccr5, Ccl2, Ccl5, and Ccl7 were among the most significantly upregulated chemokine genes in SC samples at 1 wk post-infection." (PMID 36490282, 2022). "Pulmonary arterial endothelial cells responded most rapidly to infection, with high expression of Cxcl10, Tnfsf10, and Ccl7 by 2 dpi." (PMID 34381043, 2021). "Despite different approaches, the exact roles played by CCL2 and CCL7 in recruitment of monocytes are unclear; however, we do know that lack of expression leads to a significant reduction in monocyte numbers during infection." (PMID 33829283, 2021). "CCL7 was upregulated in M1-/- mouse corneas by 9.37-fold relative to WT mouse (upregulated) after infection and has potent chemoattractant activity for a variety of leukocytes, e,g." (PMID 34653236, 2021). "Tip-DCs derived from Ly6Chi monocytes contribute to innate defense against L. monocytogenes; hence, infection is worse in mice deficient in CCL2 and CCL7 or in Ccr2-/- mice due to an increased bacterial burden." (PMID 33829283, 2021). "Of note, although the serum level of IL-6, CXCL1, and CCL7 in klotho WT mice decreased at 3 days post-infection, those in klotho KO mice was maintained until 3 days post-infection." (PMID 33329595, 2020). "CCL-7, another mediator known to participate in anti-parasitic and infection responses, was upregulated upon MOv18 IgE cross-linking only, while the classical inflammatory mediator IL-6 was not significantly changed." (PMID 33203088, 2020). "Several chemokines, including IP-10 (CXCL10), CCL2 (MCP-1), CCL3 (MIP-1α), CCL4 (MIP-1β), CCL5 (RANTES), and CCL7 (MCP-3) were also significantly increased upon infection." (PMID 32373101, 2020). "The level of CCL7 mRNA increased in the lungs of klotho WT and KO mice at 1 day post-infection and subsequently decreased at 3 days post-infection." (PMID 33329595, 2020). "Various chemokine genes, responsible for the control and recruitment of immune cells to the site of infection (i.e., Ccl2, Ccl4, Ccl5, Ccl7, Ccl8, Ccl12, and Ccl19), were also significantly upregulated in the VACV-Wyeth infected brains on 4 d.p.i." (PMID 30759813, 2019). "Amongst cytokines, the genes for Cxcl9, Cxcl10, Cxcl13, Il-1β, Il-6, Tnf, Tnfsf10, IFN-γ, Ccl2, Ccl4, Ccl7, Ccl17, and Mif were highly up-regulated (ranging from 2- to 405-fold, p ≤ 0.05), whereas Cxcl12 and Cxcl14 were down-regulated during in vivo infection." (PMID 30857242, 2019). "The increase in CCL7 with the r19FCX4C as compared with r19F infection of pHAECs is also of interest." (PMID 31330970, 2019).
infection (continued). "Two weeks post-infection, when CCL7 expression peaked at the infection site in WT mice, the CCL7 KO mice exhibited a striking 4- to 5-fold increase in immune infiltration into the infected skin." (PMID 30671055, 2018). "CCL7 add-back specifically limited neutrophil recruitment to the infection site highlighting an unexpected role for CCL7 in controlling neutrophil numbers in the L. major infected dermis." (PMID 30671055, 2018). "The increase in number of CD45+ cells and all respective subset analysis had resolved by week 4 of infection, similar to the kinetics of CCL7 expression in WT mice." (PMID 30671055, 2018). "Control or active CCL7 peptides were administered twice daily as described from day 9 to day 13 post infection, around the time of CCL7 induction in WT mice." (PMID 30671055, 2018). "We reveal a novel role for CCL7 in limiting cutaneous inflammation in response to infection with the protozoan parasite Leishmania major." (PMID 30671055, 2018). "While WT C57BL/6 mice prevented further parasite growth in the spleen, CCL7 KO mice had significantly more parasites in the spleen at 6 and 8 weeks post-infection compared to WT C57BL/6, with levels approximating those seen for susceptible WT BALB/c mice." (PMID 30671055, 2018). "In particular, the levels of I-TAC (CXCL11), IP-10 (CXCL10), MIG (CXCL9), and MCP-3 (CCL7) increased nearly 6-fold upon infection." (PMID 30467502, 2018). "CCL7 add-back led to an acute reduction in the number of neutrophils at the infection site, with minimal changes in the number of monocytes/macrophages." (PMID 30671055, 2018). "CCL7 KO mice had an increased lesion size compared to WT C57BL/6 control mice 4 weeks after infection that was resolved by 8 weeks, suggesting a possible delay in the ability to control parasite growth in the skin." (PMID 30671055, 2018). "In the context of Leishmania major infection, CCL7 is specifically upregulated in the skin one-2 weeks after infection but its role in L. major control is unclear." (PMID 30671055, 2018). "CCL7 add-back reduced the local accumulation of neutrophils at the infection site suggesting a specific role for CCL7 in limiting neutrophil influx into infected tissues." (PMID 30671055, 2018). "LysM-GFP monocyte-neutrophil reporter mice received 20 μg goat anti-CCL2 IgG, 20 μg goat anti-CCL7, or 20 μg goat IgG by intraperitoneal injection at − 12, 0, and + 12 h relative to time of infection." (PMID 29202854, 2017). "Pro-inflammatory cytokines (IFN-γ, IL-18, IL-6, TNF-α) and chemokines (CCL2, CCL5, CCL7, CXCL1, CXCL10) were found to be increased in sera of ZIKV-infected mice, indicating that infection causes systemic inflammation." (PMID 27163257, 2016). "The chemokines Ccl2, Ccl7 and Cxcl1 were also expressed at higher levels in cPLA2α−/− compared to cPLA2α+/+mice 12 h after infection, but at 24 h they decreased to a greater extent in cPLA2α−/− than cPLA2α+/+mice." (PMID 27501951, 2016). "CCL2 and CCL7 have been shown to regulate cytokine production during infection in the lung and thereby contributing to infection control and host resistance." (PMID 27014275, 2016). "These gene lists also featured a number of inflammatory cytokines and chemokines involved in chemotaxis of myeloid and lymphoid cell types to the sites of infection (Ccl4, Ccl5, Ccl7, Ccl12, Cxcl9, Cxcl10)." (PMID 23853600, 2013). "We next determined the levels of the Ccr1 agonists Ccl3, Ccl5, Ccl6, Ccl7, Ccl8 and Ccl9 in Ccr1+/+ and Ccr1−/− kidneys after infection." (PMID 22916017, 2012). "The expression of CCL chemokine ligands CCL2, CCL4 and CCL7 was significantly higher in cells infected with the mutant, relative to the cells infected with Mtb, immediately following infection at the 0 hr time-point." (PMID 22235255, 2012). "Notably, cytokine family members Ccl2, Ccl3, Ccl4, Ccl5, Ccl7, Ccl9, and Ccl22 were also significantly activated following infection." (PMID 40539063, 2025).
infection (continued). "In the WNV mouse model, CCL2 and CCL7 are important ligands for CCR2 and affect monocyte infiltration to the CNS; however, only CCL7 deficiency is associated with increased sensitivity to infection." (PMID 38997413, 2024). "We speculate that CCL2 and CCL7 produced by lung AECIIs upon VACV∆C7L infection are likely to be involved in the recruitment of CCR2+Ly6C+ monocytes into the infected areas in the lungs." (PMID 35351885, 2022). "However, at 4 h post-infection, levels of Cxcl10 and Ccl7 started to increase, also in the presence of TAT-I24." (PMID 35806257, 2022). "While clade V virus had fewer significantly differentially expressed genes, the major genes involved in cytokine storm; TNF pathway and neutrophil chemotaxis, Ccl2 and Ccl7 remained, suggesting similar, but milder presentation of pathology for its infection outcome." (PMID 36389747, 2022). "In addition, infection with Δpmi slightly decreased the expression of Ccl7 and Ccl2 in RAW264.7 cells compared with WT infection." (PMID 34491082, 2021). "The expression levels of CCL7 mRNA were comparable between klotho WT and KO mice after infection." (PMID 33329595, 2020). "This may promote the release of active TGFβ and reduce the chemotactic potential of CCL7 to attract monocytes to the site of infection." (PMID 33020210, 2020). "In the absence of CCL7, mice exhibited enhanced dermal inflammation 2 weeks post-infection that was associated with an elevated IL-17 gene signature and an increase in neutrophil recruitment." (PMID 30671055, 2018). "At later timepoints after infection, the anti-leishmania T cell response in CCL7 KO C57BL/6 mice resembled that of their WT C57BL/6 counterparts with a predominance of IFNγ producers suggesting CCL7 is not required for the priming of a protective anti-leishmania Th1 response." (PMID 30671055, 2018). "Thus, host induction of CCL7 in response to L. major infection appears critical for limiting neutrophilic inflammation in the first few weeks of infection and also protects against visceral parasite growth." (PMID 30671055, 2018). "Furthermore, CCL2 and CCL7 exhibit differential functions during infections with West Nile Virus whereby CCL7 is the critical chemokine for virus clearance and survival." (PMID 29953538, 2018). "Elevated CCL7 protein expression at the infection site peaked 1 and 2 weeks post-infection." (PMID 30671055, 2018). "Limiting cutaneous inflammation following L. major infection via CCL7 may have potential therapeutic application for locally controlling the inflammation at the infection site and attenuating visceral parasite growth." (PMID 30671055, 2018). "CCL7 may also work indirectly, by promoting the accumulation of myeloid cells to the infection site that might compete for, or inhibit, signals that enhance neutrophil accumulation." (PMID 30671055, 2018). "CXCL1, CCL2, and CCL7 in the lungs were significantly increased in aged mice after infection." (PMID 30018181, 2018). "Furthermore the increase in levels of CXCL10 and CCL7 occurred subsequently to the infection-induced upregulation of IFN-γ, since peak levels for this cytokine were reached in C57BL/6 mice 2–3 days earlier." (PMID 23762028, 2013). "In our model, some chemokines reported to be part of the "1st and 2nd waves" of chemokine expression by DC cells, specifically Xcl1, Cxcl9, Cxcl16, Ccl1, Ccl2, Ccl3, Ccl4, Ccl5, Ccl7 and Ccl8 are expressed at increased levels in lung i.n. samples at 3 weeks post-infection." (PMID 20942964, 2010). "Particularly in dLNs, enhanced production of Ccl8 and Ccl7 was observed in CD1d-KO mice compared with WT mice, which, being monocyte and DC chemoattractants, could enhance the trafficking of those cells infected already as well as potential infection targets." (PMID 39088280, 2024).
infection (continued). "At the molecular level, the diminished recruitment of inflammatory monocytes seen in the Δnrp strain may be explained by a lower expression of CCL2 and CCL7, chemokines that play a role in the recruitment of myeloid cells to the site of infection, in the lungs of these animals." (PMID 30381350, 2018). "After infection, the expression levels of CXCL10, Saa3, and CCL7 were found to be elevated across all viral-infected groups." (PMID 40338080, 2025). "In contrast, 4T1-upregulated Ccl7, Ccl12 and Ccl22 (most strongly upregulated by SFV/TNFα) were even more upregulated after infection." (PMID 40547518, 2025). "On the other hand, infection with SFV/TNFα specifically upregulated the amount of IL-6, CCL2, CCL3, CCL7 and CCL20 (p < 0.0001)." (PMID 40547518, 2025). "MCP3/CCL7 draws monocytes, T cells, and dendritic cells to infection sites, while MIG/CXCL9 attracts T cells and natural killer cells." (PMID 39052548, 2024). "Regarding inflammatory response, ChP organoids showed an increase in inflammatory cytokines CCL7, interleukin-32 (IL-32), CCL2, MCP1, IL-18, and IL-8 upon infection." (PMID 35337041, 2022). "We confirmed a MDA5/STING-dependent upregulation of cytokine and chemokine genes after VACV∆C7L infection in AECII cells, including Ifnb1, Ccl2, Ccl7, Ccl4, Ccl5, and Cxcl10." (PMID 35351885, 2022). "It is reported that the infection of microsporidia Encephalitozoon cuniculi up-regulated expression of CCL1, CCL2, CCL3, CCL7 and other chemokines." (PMID 36015036, 2022). "In the current setting, transcript levels of the chemokines Cxcl10 and Ccl7 were also rapidly upregulated upon MCMV infection and reduced by TAT-I24 2 h post-infection." (PMID 35806257, 2022). "SARS-CoV-2 infection also resulted in many cytokines and chemokines above baseline levels (all P < 0.05) throughout the infection, including IFN-γ, IL-1β, IL-4, IL-28, CXCL10, GM-CSF, LIF, CCL2, CCL7, MIP-1α, MIP-1β, RANTES, IFN-α, and IFN-β." (PMID 35634338, 2022). "In the very early stage of infection, chemokines such as IL-8 (CXCL8), MCP-3 (CCL7), and RANTES (CCL5) are produced by numerous cell types." (PMID 33483611, 2021). "BothCCL2 and CCL7 and their receptors were downregulated.CCL2 and its receptors, CCR2 andCCR4, act to recruit monocytes and macrophages to the site of infection.The majority of chemokines were significantly up-regulated." (PMID 32347041, 2021). "Proteins highlighted in green (e.g., CCL2=MCP-1, CCL7=MCP-3, CCL8=MCP-2, CXCL10=INP10, are proteins known to be elevated in blood after infection for example with M. tuberculosis." (PMID 35145507, 2021). "Several chemokines were induced quickly in the early phase (day 2 p.i.)and maintained at a rather high level through the first week of infection, including CCL2, CCL3, CCL4, CCL7, CXCL10, IL-6, IFN-γ, CCL11, CCL5, TNF-α, CXCL1, IL-4, IL-12p70." (PMID 34379705, 2021). "Following infection, only XCL1 and CCL7 mRNAs were significantly increased in the spleen of WT mice on day 3 postinfection, which declined to the mock-infected levels on day 7 postinfection and remained low at day 35 postinfection." (PMID 32310998, 2020). "To examine the pHAECs response to infection by the two viruses, we determined the mRNA levels for RSV M as well as those of IL-6, CX3CL1, CCL7 (MCP-3), Muc5AC, and Muc5B." (PMID 31330970, 2019). "Infection with the ΔgliP mutant significantly stimulated the expression of CXCL2, CCL3, CCL4, CCL7, TNF-α, and IL-6, whereas infection with the Δaspf1 ΔgliP double mutant significantly decreased the expression of CXCL2, CCL7, TNF-α, and IL-6." (PMID 30052103, 2018). "LTB4/BLT1 axis is required for the synthesis of chemokines that recruits neutrophils (CXCL1 and CXCL2), monocytes (CCL2, CCL8, and CCL7) and T cells (CCL4) at both days 1 and 9 after infection." (PMID 30102746, 2018). "The infection of sham-operated mice with MCMV resulted in the induction of a different chemokine subset containing Ccl12, Ccl7, Ccl4 and Cxcl10." (PMID 29953538, 2018).